CNTNAP2 (contactin associated protein 2)
Diseases named in the same sentence as CNTNAP2 in open-access papers (continued):
Sharing a sentence is not in itself a finding about the gene and the disease.
Alzheimer disease (5 papers, 2011 to 2025). A progressive, neurodegenerative disease characterized by loss of function and death of nerve cells in several areas of the brain leading to loss of cognitive function such as memory and language. "Markunas and colleagues showed that DNA methylation is changed in 110 gene regions and notably FRMD4A, a gene associated with Alzheimer disease (AD) and nicotine dependence and CNTNAP2, a gene associates with neural development, autism spectrum disorder, schizophrenia, and language impairment." (PMID 40115268, 2025). "A study on late-onset Alzheimer’s disease focusing on protein–protein network interactions revealed eight genes with strong associations: APOE, SORL1, APOC1, CD33, CLU, TOMM40, CNTNAP2, and CACNA1C." (PMID 39228919, 2024). "Notably, CNTNAP2 expression is decreased in the hippocampus of Alzheimer’s disease (AD) patients due to the downregulation by STOX1, supporting the association between CNTNAP2 level and memory." (PMID 37089693, 2023).
breast carcinoma (5 papers, 2014 to 2024). "When we initiated this study, we believed that the CNTNAP2 gene would be a strong candidate for lymph node status because of its association with metastatic spread to the axillary lymph nodes in breast carcinoma." (PMID 24885002, 2014). "Predictions of known cancer driver genes in new cancer types include SPTA1, CHD4 and ASXL1 in colorectal cancer, FOXO3, MUC16 and ZFPM1 in breast cancers and CNTNAP2, CTNND2 and TRRAP in lung adenocarcinoma." (PMID 38890488, 2024). "The method reveals that ESR1, FGFR2, VDR, CNTNAP2, and BRCA2 have a weak association with sporadic breast cancer in the Uruguayan population." (PMID 33126731, 2020). "We found weak evidence for the association of risk variants rs294174 (ESR1), rs16886165 (MAP3K1), rs2214681 (CNTNAP2), rs4237855 (VDR), rs9594579 (RANKL), rs8183919 (PTGIS), rs2981582 (FGFR2), and rs1799950 (BRCA1) with sporadic breast cancer." (PMID 33126731, 2020). "Nonetheless, three genes (CNTNAP2, EHF, KDM4B) were significantly upregulated by DHT in all four models of breast cancer and displayed enrichment of AR, GATA3, and H3K27ac ChIP-seq signals at associated genomic loci." (PMID 38317241, 2024).
developmental delay (5 papers, 2013 to 2024). "The seven patients in our cohort exhibit a typical CNTNAP2 core phenotype, including global developmental delay with expressive language disturbances in all (7/7, 100%) and behavioral abnormalities in most (5/7, 71%)." (PMID 37805811, 2024).
specific language impairment (5 papers, 2011 to 2022). A language disorder characterized by difficulty in language acquisition despite otherwise normal development and in the absence of any obvious explanatory factors. "Multiple genetic studies have identified genes, such as contactin-associated protein-like 2 (CNTNAP2), and genetic loci, particularly on chromosome 7, which are associated with both ASD and specific language impairment." (PMID 30348077, 2018).
COVID-19 (4 papers, 2022 to 2025). A disease caused by infection with severe acute respiratory syndrome coronavirus 2. "Neurological manifestations in COVID-19 patients have been associated with the presence of autoantibodies against contactin-associated protein 2 (anti-Caspr2), GD1b ganglioside (anti-GD1b), myelin oligodendrocyte glycoprotein (anti-MOG), and myelin basic protein (anti-ObM)." (PMID 41009363, 2025). "GWAS identified candidate genes common to both COVID-19 severity and PASC, including CNTNAP2, WWOX, and ADAMTS17, which are implicated in extracellular matrix remodeling and neurological and cognitive development." (PMID 41561974, 2025). "In the COVID-19 group, coagulation factor XIII A chain (F13A1) and contactin associated protein 2 (CNTNAP2) exhibited the strongest upregulation, with CD14, C1QC, cytochrome C oxidase subunit 7C (COX7C) and (APOE) being increased in the AD group." (PMID 36211330, 2022).
neuroblastoma (4 papers, 2009 to 2024). Neuroblastoma (NB) is the most common solid, extracranial childhood tumor. "In order to find an explanation for the low expression in unfavourable neuroblastoma tumours, we scrutinized SNP microarray data from six unfavourable tumours to search for deletions and other copy number aberrations of the CNTNAP2 gene." (PMID 19686582, 2009).
oligodendroglioma (4 papers, 2022 to 2025). A well-differentiated (WHO grade II), diffusely infiltrating neuroglial tumor, typically located in the cerebral hemispheres. "As a notably large gene located on chromosome arm 7q, CNTNAP2 has been identified as a tumor suppressor in diffuse gliomas, with specific mutations documented in oligodendrogliomas." (PMID 40426960, 2025). "Both PTPRD and CNTNAP2 exhibit recurrent mutations in all subtypes of diffuse gliomas, including oligodendrogliomas." (PMID 40426960, 2025). "In aggressive oligodendroglioma, CNTNAP2 expression decreases and is associated with reduced overall survival." (PMID 38877096, 2024). "Strikingly, low CNTNAP2 expression (below 7.8) was detected in a subpopulation of oligodendrogliomas and associated with poor patient survival (p = 0.0042, log-rank test)." (PMID 35982066, 2022). "Taken together, the data support previous reports about the tumor suppressor role of PTPRD and CNTNAP2 in diffuse gliomas and show that low CNTNAP2 expression is associated with poor overall survival especially in oligodendrogliomas." (PMID 35982066, 2022). "Our analysis revealed that PTPRD and CNTNAP2 are recurrently altered in all diffuse glioma subtypes, also in oligodendroglioma, and low expression of these genes was associated with poor patient prognosis." (PMID 35982066, 2022). "Maximum time-lapse from diagnosis to death was 30 months for oligodendroglioma cases with low expression of CNTNAP2 or both CNTNAP2 and PTPRD." (PMID 35982066, 2022). "In The Cancer Genome Atlas (TCGA) diffuse glioma cohort, PTPRD and CNTNAP2 expression decreased by tumor grade in oligodendrogliomas and PTPRD expression also in IDH-mutant astrocytomas." (PMID 35982066, 2022). "Our analysis of primary and recurrent oligodendrogliomas revealed rearrangements in CNTNAP2 and PTPRD genes in the recurrencies, which were originally diagnosed as secondary GBMs because they showed histological signs of tumor progression." (PMID 35982066, 2022). "Although oligodendrogliomas typically have the best prognosis among diffuse gliomas, a decrease in protein tyrosine phosphatase receptor type D (PTPRD) and contactin-associated protein 2 (CNTNAP2) gene expression can indicate more aggressive tumor development." (PMID 39062515, 2024). "The survival rates were poor for oligodendroglioma cases with low expression of both PTPRD and CNTNAP2 (median 8 months, maximum 30 months)." (PMID 35982066, 2022). "PTPRD and CNTNAP2, which are recurrently altered in diffuse gliomas and show decreased expression in a subpopulation of patients, could be informative for the stratification of these aggressive oligodendrogliomas by analyzing their inactivating alterations and gene expression levels." (PMID 35982066, 2022). "Our analysis provides information about aggressive oligodendrogliomas with worse prognosis and suggests that PTPRD and CNTNAP2 expression could represent an informative marker for their stratification." (PMID 35982066, 2022).
fragile X syndrome (3 papers, 2023 to 2025). A genetic syndrome caused by mutations in the FMR1 gene which is responsible for the expression of the fragile X mental retardation 1 protein. "Increased variability has been observed in the olfactory bulb of Shank3B−/− and Cntnap2−/− knock-out mice and the Fmr1 knock-out (KO) mouse model of fragile X syndrome." (PMID 41062277, 2025).
Obesity (3 papers, 2015 to 2021). Accumulation of substantial excess body fat. "Mutations in Cntnap2 in mice impair Kv1.1 localization, and can be obesity-promoting or obesity-resistant in diet-induced obesity depending on genetic background." (PMID 25760438, 2015). "CNTNAP2 is amongst genes that lie within regions of de novo duplications and deletions recently linked to syndromic obesity in children." (PMID 25760438, 2015). "CNTNAP2, GLI2, DPT (dermatopontin), AEBP1, ITIH5, CXCL11, GDNF (glial cell derived neurotrophic factor), MCHR1, FLT3, ELANE (elastase, neutrophil expressed), OSMR (oncostatin M receptor) and IL15RA are involved in development of obesity, but these genes might be key for progression of HF." (PMID 34218797, 2021).
speech disorder (3 papers, 2011 to 2020). A term referring to disorders characterized by the disruption of normal speech. "It was found to be a direct neural target of the human FOXP2 protein, and mutations of FOXP2 and CNTNAP2 were linked to language and speech disorders in ASD." (PMID 28105001, 2016). "Speech disorders, behavioral disturbances, and other neuropsychiatric disorders have been identified in patients with alterations in the CNTNAP2 gene." (PMID 33042910, 2020).
type 2 diabetes (3 papers, 2016 to 2025). "Other consistent loci involve CNTNAP2 (contactin associated protein-like 2) and have been reported associated with several mental diseases, as well as KCNQ1 (voltage-gated KQT-like subfamily Q, member 1) that has been associated with type 2 diabetes." (PMID 31277270, 2019).
Brain atrophy (2 papers, 2024). Partial or complete wasting (loss) of brain tissue that was once present. "Associations with language, cognitive and brain atrophy measures were found with CNTNAP2 and PRNP genetic variability." (PMID 38828303, 2024).
brain tumor (2 papers, 2009 to 2023). "McAvoy and colleagues found that CNTNAP2 was inactivated in brain tumours, which together with our findings support a tumour suppressor function of CNTNAP2 in neural cells." (PMID 19686582, 2009).
cognitive decline (2 papers, 2021 to 2024). "Among these high-risk genes, those dysregulated in more than one cell type, such as CNTNAP2 and SORL1, may represent potential targets to defer the onset of cognitive decline and neurodegenerative diseases in the elderly." (PMID 34052996, 2021).
colon cancer (2 papers, 2008 to 2022). "When locations were compared, 2 signals were detected when comparing left and right colon cancers (the most significant genetic variant was located in the FERMT2 gene) and 3 when comparing rectal vs colon cancers (the most significant genetic variant was located in CNTNAP2 gene)." (PMID 36077729, 2022).
exfoliation syndrome (2 papers, 2012). An autosomal dominant disorder caused by mutations in the LOXL1 gene, encoding lysyl oxidase homolog 1. "Intriguingly, variants in CNTNAP2 were also implicated in pseudoexfoliation syndrome among patients who show a selective downregulation of clusterin (CLU) expression in their eyes." (PMID 22384383, 2012). "CNTNAP2 allele frequencies in patients with exfoliation syndrome and in controls in Japanese." (PMID 22690117, 2012). "Frequency of genotypes CNTNAP2 gene in patients with exfoliation syndrome and in controls in Japanese." (PMID 22690117, 2012). "A GWAS was recently performed using a DNA-pooling approach, and a single genotype at the contactin-associated protein-like 2 (CNTNAP2) locus had significant associations between XFS and exfoliation glaucoma and two SNPs (rs2107856 and rs2141388)." (PMID 22690117, 2012).
glioblastoma (2 papers, 2022 to 2026). The most malignant astrocytic tumor (WHO grade IV). "In the TCGA cohort of 581 diffuse gliomas, the lowest CNTNAP2 expression was observed in IDHwt glioblastoma tumors." (PMID 35982066, 2022). "In the TCGA rearrangement cohort of 59 diffuse gliomas, intragenic CNTNAP2 rearrangements were detected in four tumors, including three IDHwt glioblastomas and one IDHmut astrocytoma." (PMID 35982066, 2022).
inflammatory bowel disease (2 papers, 2023). A spectrum of small and large bowel inflammatory diseases of unknown etiology. "In the GI tract, CNTNAP2 has been associated with inflammatory bowel disease, and Cntnap2−/− mice have increased intestinal permeability." (PMID 37131706, 2023).
melanoma (2 papers, 2022 to 2025). A malignant, usually aggressive tumor composed of atypical, neoplastic melanocytes. "Tumor suppressor gene CNTNAP2 has frequently clonal mutation in melanoma." (PMID 35962343, 2022).
nicotine dependence (2 papers, 2019). Physical and psychological dependence on nicotine. "Other genes highlighted in our EWAS with genetic variants associated with smoking-related phenotypes include LSM6 and CNTNAP2 associated with nicotine dependence and CACNA2D4 with pack years (indicator of lifelong accumulated smoking exposure)." (PMID 30611298, 2019).
aging (1 paper, 2019). A developmental process that is a deterioration and loss of function over time. "The polymorphism in the CNTNAP2 gene has been found to take part in many aging diseases." (PMID 31649738, 2019).
alcohol addiction (1 paper, 2019). "Several rare variants in the CNTNAP2 gene were also implicated in alcohol addiction in a previous study." (PMID 31446765, 2019). "The authors suggested that 97 rare variants of the CNTNAP2 gene could be protective against alcohol addiction in women." (PMID 31446765, 2019). "CNTNAP2 gene was previously identified in alcohol addiction." (PMID 31446765, 2019).
apraxia of (1 paper, 2021). "Mutations in FOXP2 are a monogenic cause of childhood apraxia of speech (SPCH1, OMIM #602081) and CNTNAP2 is functionally implicated in the aetiology of this condition as part of the downstream network of FOXP2 target genes." (PMID 34641913, 2021).
communication disorder (1 paper, 2011). A disorder characterized by an individual's inability to comprehend or share ideas or feelings because of an impairment in language, speech, or hearing. "In terms of theoretical implications, it is clear that these common CNTNAP2 variants are not sufficient by themselves to account for language and communication disorders in children." (PMID 21310003, 2011).
convulsion (1 paper, 2010). A rapid and repeated body muscle contract that results in an uncontrolled shaking of the body. "Finally, we identified one proband with neonatal convulsions (NC) carrying a deletion within the CNTNAP2 gene that spans exons 2–4 as well as a 370-kb deletion of 17p13 involving 7 genes." (PMID 20502679, 2010).
epileptic syndrome (1 paper, 2022). "From a genetic perspective, intragenic deletions of the contactin-associated protein-like 2 gene (CNTNAP2) have been found in patients with epileptic syndrome and stuttering." (PMID 35455763, 2022).
esophageal carcinoma (1 paper, 2024). A primary or metastatic malignant neoplasm involving the esophagus. "GABRG2, CNTNAP2, and SCN4B in the hub genes have high diagnostic value in determining whether hypopharyngeal carcinoma patients have combined esophageal carcinoma (AUC: 0.944, 0.944, 0.972)." (PMID 38877096, 2024).
head and neck squamous cell carcinoma (1 paper, 2024). A squamous cell carcinoma that arises from any of the following anatomic sites: lip and oral cavity, nasal cavity, paranasal sinuses, pharynx, larynx, and salivary glands. "In a study of head and neck squamous cell carcinoma, CNTNAP2 has some predictive ability for the sensitivity of laryngeal squamous cell carcinoma to induction chemotherapy." (PMID 38877096, 2024).
oral cancers (1 paper, 2014). "In a genome-wide association study for oral cancers, CNTNAP2 was found to be associated with cell migration." (PMID 24885002, 2014).
oral squamous cell carcinoma (1 paper, 2026). "In parallel, the short isoform CNTNAP2-203 has recently emerged as an oncogenic driver in oral squamous cell carcinoma, where its selective upregulation amplifies EGFR-E2F1 signaling and promotes tumor progression." (PMID 42110583, 2026).
pancreatic cancers (1 paper, 2013). "Although a large-scale screening study of pancreatic cancers has identified CNTNAP2 as one of the genes that are methylated in cancer cells, the clinicopathological impact of DNA methylation of the CNTNAP2 gene has not yet been elucidated in human malignancies." (PMID 23544068, 2013).
periodontal disease (1 paper, 2025). "The most robust associations found for each phenotype are as follows: DMFT with rs79198416 (near CDC73/KCNT2; p = 7.57E-07), periodontal disease with rs73870587 (DIPK2A, p = 7.38E-08); CIMT with rs113152669 (LRP1Bp = 4.07E-07), and CAC with rs76676138 (CNTNAP2; p = 2.47E-19)." (PMID 41006734, 2025).
Polydipsia (1 paper, 2023). Excessive thirst manifested by excessive fluid intake. "The effects of other genes such as the neurexin family gene, CNTNAP2, and SHANK2 gene on polydipsia remained to be clarified." (PMID 37484674, 2023).
scoliosis (1 paper, 2020). A congenital or acquired spinal deformity characterized by lateral curvature of the spine. "Moreover, some genome-wide studies have detected in patients with scoliosis a single nucleotide polymorphism in genome regions that code for proteins implicated in vestibular development (CHL 1) and vestibular function (Cntnap2)." (PMID 32503240, 2020).
Williams-Beuren syndrome (1 paper, 2013). "Five patients who had deletions in NRXN1 had a second CNV implicated in neurodevelopmental disorder: a CNTNAP2 and CSMD3 deletion in patients with exonic NRXN1 deletions, and a Williams-Beuren syndrome deletion and two 22q11.2 duplications in patients with intronic NRXN1 deletions." (PMID 25408897, 2013).